CRP (C-reactive protein)
Diseases named in the same sentence as CRP in open-access papers (continued):
Sharing a sentence is not in itself a finding about the gene and the disease.
Insulin resistance (continued). "Type 1 DM is induced by the chronic inflammation of pancreatic islets, while type 2 DM is associated with insulin resistance resulting in elevated production of inflammatory markers such as C-reactive protein (CRP), IL-6, and TNF-α." (PMID 29370858, 2018). "Other studies have shown that weight loss after gastroplasty progresseswith decreased circulating levels of interleukin-6 and CRP in association withimproved insulin resistance." (PMID 30539977, 2018). "Eventually, increased serum levels of PAI-1, ET- 1, tumor necrosis factor-α (TNF-α), interleukin-6 (IL-6), and C-reactive protein (CRP), reflect association of insulin resistance with low-grade inflammation and endothelial dysfunction." (PMID 30170601, 2018). "Fasting glycated haemoglobin, glucose, insulin, and C-Reactive Protein (CRP) were measured and indices of metabolic risk were derived (homeostatic model of insulin resistance, HOMA-IR and metabolic risk z-score)." (PMID 28711418, 2018). "Some significant associations of insulin resistance index and C-reactive protein with selected domains of cognitive were also detected." (PMID 30002734, 2018). "A low C-HDL, and high levels of NEFA, triglycerides, IL-6, TNF-α and CRP have been previously implicated in the development of insulin resistance." (PMID 30400254, 2018). "Estimated VO2 max was inversely associated with FMI, fasting insulin, HOMA‐insulin resistance (IR), HbA1c, fasting glucose, urate, CRP, triglyceride, LDL‐cholesterol, and systolic and diastolic BP, and positively associated with HDL‐cholesterol." (PMID 29411507, 2018). "We examined the associations of leptin, hs (high sensitivity)- CRP and insulin resistance with bone turnover markers (BTMs) and bone characteristics in 55 young obese adults (median BMI 40 kg/m2) and 65 non-obese controls." (PMID 28640843, 2017). "Higher levels of CRP, high sensitivity CRP (hsCRP), and IL-6 have consistently been associated with an increased risk of insulin resistance, hyperinsulinism, impaired glucose tolerance, type 2 diabetes, and metabolic syndrome." (PMID 28753646, 2017). "Tumor necrosis factor (TNF)-α, interleukin (IL)-6 and c-reactive protein (CRP), are important pro-inflammatory cytokines induced by elevated triglyceride concentrations which have been linked to insulin resistance." (PMID 28555043, 2017). "For instance, higher insulin resistance (IR) and C-reactive protein (CRP) have been prospectively associated with greater risk of frailty among adults aged 69 to 74 years participating in the Cardiovascular Heart Study (CHS)." (PMID 28400989, 2017). "This association was only modestly explained by insulin resistance and chronic inflammation, as measured by CRP." (PMID 28400989, 2017). "LBP is also demonstrated to associate with high sensitivity C- reactive protein (hs-CRP), insulin resistance, dyslipidemia, and cytokeratin-18 fragment level." (PMID 28107471, 2017). "The levels of insulin, ultrasensitive C-reactive protein and uric acid were also associated with insulin resistance." (PMID 28492722, 2017). "We found that metformin ameliorates insulin resistance and dyslipidemia and exhibit cardioprotective effects by reducing inflammation and tissue oxidative and dicarbonyl stress associated with human CRP." (PMID 26963617, 2016). "In humans, consumption of 600 mg/day grape seed extract for 4 weeks improved insulin resistance and markers of inflammation such as blood C-reactive protein concentration in patients with type 2 diabetes at high risk for cardiovascular disease." (PMID 27977712, 2016). "The regulation of triglyceride levels is associated with inflammation and insulin resistance; therefore, increased triglyceride levels for both the ε4 and non-ε4 carriers in the high CRP group are acceptable." (PMID 27177774, 2016).
Insulin resistance (continued). "We determined that the homeostasis model assessment-estimated insulin resistance and CRP–Alb ratio were independent risk determinants for SMM/wt (βHOMA-IR = −0.18 and βCRP–Alb ratio = −3.84, adjusted R2 = 0.32)." (PMID 27768746, 2016). "Discovered from the plasma of patients with acute inflammation first, CRP is an independent risk factor for synthesizing macrophage inflammatory factors and developing insulin resistance." (PMID 27127795, 2016). "CRP has been identified as a major player in the pathological process associated with MetS as CRP is associated with insulin resistance, endothelial dysfunction and impaired fibrinolysis." (PMID 25906072, 2015). "During pregnancy, increased CRP levels are associated with insulin resistance, maternal dysglycemia, and GDM." (PMID 25915047, 2015). "CRP, a classic acute-phase reactant, is a sensitive marker of inflammation in numerous pathologic conditions, and elevated CRP levels have been associated with abnormal metabolic conditions such as insulin resistance, hyperglycemia, and T2DM." (PMID 25915047, 2015). "There were no significant treatment effects on total or HDL cholesterol, TGs, CRP, homeostatic model assessment of insulin resistance, blood pressure, or the Framingham 10-y CHD risk score." (PMID 26446482, 2015). "Upon administration of HET, we observed a significant reduction in serum cytokine levels and CRP associated with a decrease in insulin resistance." (PMID 26003803, 2015). "C-reactive protein (CRP), which is an inflammatory biomarker induced by IL-6, was increased by insulin resistance and was associated with an increased risk of endometrial cancer in postmenopausal women." (PMID 25866823, 2015). "Higher intramuscular adipose tissuewas strongly associated with insulin resistance and higher serum inflammatory markers including C-reactive protein, interleukin-6, and tumor necrosis factor-alpha." (PMID 26030144, 2015). "The causal pathways and time sequence between elevated CRP levels and central obesity, insulin resistance, and the metabolic syndrome are complicated and remain largely unresolved." (PMID 25163828, 2014). "Central obesity, insulin resistance, inflammatory marker (CRP), and dyslipidemia are well-established risk factors of MetS." (PMID 24883062, 2014). "In a study that included 94 patients with RA, Dessein and Joffe observed that insulin resistance was associated with markers for inflammation such as C-reactive protein and erythrocyte sedimentation rate and disease activity scores." (PMID 23431244, 2013). "It was reported previously that both insulin deficiency and insulin resistance were associated with increased production of CRP." (PMID 23717483, 2013). "Another feature of insulin resistance is the association with inflammatory markers (e.g. C-reactive protein, prostaglandin PGE2, pro-inflammatory cytokines) and high oxidative stress." (PMID 22314022, 2012). "CRP, an inflammatory agent common in numerous pathologic conditions, has been associated with metabolic abnormal states such as insulin resistance, hyperglycemia, and T2DM, while it also appears to be associated with central obesity." (PMID 22550485, 2012). "Inflammation, demonstrated primarily by elevated levels of serum C-reactive protein, is thought to be associated with insulin resistance and MS." (PMID 21822486, 2012). "Pearson's correlation test showed an association between CRP and insulin resistance indexes before intervention (p=0.02, r=0.34)." (PMID 22737516, 2011). "During the last few years, insulin resistance has been shown to be strongly associated with CRP and body fat, particularly visceral fat." (PMID 21167068, 2010). "C-reactive protein levels (strongly associated with insulin resistance and type 2 diabetes risk) are also elevated." (PMID 20421924, 2010). "First, because of this cross-sectional data collection design, we cannot be certain of the temporal relation between elevated CRP concentration and risk of insulin resistance." (PMID 20482756, 2010).
Insulin resistance (continued). "The vegan group also showed significantly lower levels of CRP, a physiologic marker of subclinical inflammation, which has been shown to be associated with insulin resistance and CVD." (PMID 18348715, 2008). "Overall, SAD showed a slightly higher correlation with most cardiovascular risk factors, especially insulin resistance, insulin, CRP, apolipoprotein B and triglycerides (all P-values < 0.01) than other anthropometric measures." (PMID 17391519, 2007). "There is a need for better, cheaper and non-invasive markers of cardiovascular risk factors including hypercholesterolemia, hypertension, insulin resistance and elevated CRP levels." (PMID 17391519, 2007). "In general, SAD was a stronger predictor of cardiovascular risk factors, especially of insulin resistance, apoB, insulin, triglycerides and CRP, than the other anthropometric measures." (PMID 17391519, 2007). "The Paleolithic group also showed significantly lower levels of C-reactive protein, a physiologic marker of subclinical inflammation, which has been shown to be associated with insulin resistance and cardiovascular disease." (PMID 17081292, 2006). "In the present cohort of unselected RA patients, IL-6 was more strongly associated with endothelial dysfunction than were CRP, erythrocyte sedimentation rate and insulin resistance." (PMID 15899050, 2005). "Excessive consumption of red meat has been associated with C-reactive protein (CRP) concentration, insulin resistance, oxidative stress, and inflammation, which may affect glucose metabolism and blood inflammation intensity." (PMID 41499450, 2026). "Values were classified as follows: HbA1c (normal: < 5.7%, high: ≥ 5.7%); triglycerides (normal: < 150 mg/dL, high: ≥ 150 mg/dL); LDL‐c (normal: < 130 mg/dL, high: ≥ 130 mg/dL); HOMA2‐IR (normal: ≤ 1.8, insulin resistance: > 1.8; CRP (low or moderate risk: ≤ 3 mg/L, high risk: > 3 mg/L)." (PMID 41559012, 2026). "Concentration of serum calprotectin also showed a positive association with CRP, HbA1c, early insulin resistance, unfavorable changes in lipid profile and low adiponectin levels, suggesting its potential role as a laboratory biomarker of early disturbances in glucose and lipid metabolism." (PMID 41440998, 2025). "There is a view that H. pylori infection increases the risk of cardiovascular conditions, insulin resistance, and metabolic syndrome, with possible causal pathways that involve elevations in inflammatory markers such as C-reactive protein (CRP) and Interlukin-6 (IL-6)." (PMID 41470170, 2025). "On the detrimental side, IL-6 is a key upstream driver of hepatic CRP synthesis and has been linked to endothelial dysfunction, insulin resistance, and systemic inflammatory activation, all of which may accelerate vascular complications in T1D." (PMID 41010714, 2025). "At an FDRBH < 0.05, significant covariance was observed with respect to air pollution exposure (r = –0.11) and body mass index (BMI, r = 0.27), while C-reactive protein (r = –0.47) and homoeostatic model assessment of insulin resistance (HOMA-IR, r = 0.42) were nominally associated." (PMID 39271751, 2025). "The introduction of MAFLD has brought about a notable transformation in liver disease classification by incorporating metabolic abnormality indicators, such as insulin resistance, heightened sensitivity to C-reactive protein (CRP), and other complex metabolic risk factors." (PMID 40559394, 2025). "Among circulating proinflammatory markers, C-reactive protein (CRP) and interleukin-6 (IL-6) have been extensively studied and are consistently associated with insulin resistance, endothelial dysfunction, and increased risk of cardiovascular events and mortality in T2D." (PMID 40629349, 2025). "Elevated CRP has not only been observed in patients with RA, but may also be associated with the development of induced insulin resistance and T2D by inhibiting insulin signaling." (PMID 39430749, 2024).
Insulin resistance (continued). "This study aimed to investigate whether low-density lipoprotein (LDL) cholesterol, homeostatic model assessment (HOMA) for insulin resistance, and C-reactive protein (CRP) served as mediators in this association across a sample of 18,435 US adults." (PMID 38611646, 2024). "Furthermore, limited sitting time has been associated with a lower risk of metabolic syndrome, insulin resistance, and improved C-reactive protein levels." (PMID 38536210, 2024). "CRP, another inflammatory mediator, is produced by both adipocytes and the liver in response to IL-6; circulating levels of hs-CRP are considered markers for cardiovascular disease risk and have been linked to insulin resistance." (PMID 39062848, 2024). "Moreover, these cytokines and inflammatory mediators, particularly TNF-α, monocyte chemotactic protein-1 (MCP-1), CRP, and interleukins, are considered as the potential cause of insulin resistance or impaired B cell function." (PMID 36769405, 2023). "The prediction of future metabolic risk by CRP might in part be accounted by its role as a proxy of insulin resistance in pregnancy, but it still offers the advantage of being a useful marker in pregnancy that does not need to be measured in a fasting state." (PMID 37891561, 2023). "Regarding cross-sectional associations in the early postpartum, CRP correlated with higher weight and body fat, increased insulin resistance (higher HOMA-IR and lower MATSUDA), absolute insulin secretion (HOMA-B and AUCins/glu) and reduced relative insulin secretion (ISSI-2) (all p ≤ 0.009)." (PMID 37891561, 2023). "In the SHR-CRP rats, disturbances in glucose and lipid metabolism were secondary to inflammation associated with transgenic expression of human C-reactive protein, while insulin resistance and hepatic steatosis in HHTg rats were secondary to hereditary hypertriglyceridemia." (PMID 36837811, 2023). "We hypothesised that chronic, acute, and acute-on-chronic hyperglycaemia might impact CRP levels during hospitalisation and that high CRP levels at admission are associated with increased insulin resistance in patients with CAP." (PMID 38202252, 2023). "Therefore, CRP deficiency raises the efficacy that central leptin controls hepatic glucose flux and improve hepatic insulin resistance induced by lipid infusion." (PMID 37660067, 2023). "The prospective association of CRP with increased insulin resistance and reduced adjusted insulin secretion hint to the role of inflammation in the development of impaired metabolism after GDM and could be used as an early marker for risk stratification." (PMID 37891561, 2023). "By activating nuclear factor kappa B (NF-κB), a rise in CRP might cause apoptosis in β-cells and contribute to insulin resistance." (PMID 38004306, 2023). "In addition, we found that increasing admission CRP levels were associated with higher levels of insulin resistance." (PMID 38202252, 2023). "One study investigated the association between sugar in solids and liquids and markers of metabolic risk (notably serum Hemoglobin A1c, HbA1c, serum C-reactive protein, Homeostasis Model Assessment of Insulin Resistance, HOMA-IR, and the metabolic risk z-score)." (PMID 37851689, 2023). "By constructing the PCOS model, we found that CRP knockout rats showed better glucose disposal ability and higher insulin sensitivity than wild-type rats in GTT and ITT tests, which further reflected that CRP may be implicated in insulin resistance in PCOS." (PMID 37660067, 2023). "Smoking results in insufficient secretion of insulin and insulin resistance via ß-cell dysfunction, oxidative stress, inflammation, and increased level of C reactive protein (CRP) that may promote the risk of cardio-metabolic dysfunction." (PMID 37237334, 2023). "It has been suggested that high CRP levels may be strongly associated with central adiposity, insulin resistance, blood pressure, high TG, and low HDL." (PMID 37645243, 2023).
Insulin resistance (continued). "The secondary outcomes were to determine whether date fruit affected cardiovascular risk by measuring fasting lipids, C-reactive protein (CRP), blood pressure, and insulin resistance (IR) as measured by Homeostatic Model Assessment (HOMA-IR)." (PMID 36079749, 2022). "As follow-up analysis, hierarchical multiple regression was used to assess the interaction effect of continuous insulin resistance with serum Mg2+ and analyzed by multivariable linear regression on the association of outcome variables: HbA1c, BMI, Log10 hs-CRP and Log10 Leptin." (PMID 35440685, 2022). "Reductions in CRP occurred in parallel with bodyweight loss and were positively correlated with reductions in bodyweight, waist circumference, fasting plasma glucose, fasting serum insulin, and homeostatic model assessment of insulin resistance." (PMID 36467859, 2022). "Participants from the Lanoh community showed a higher risk of diabetes, which could be due to insulin resistance, compared with other sub-tribes as the high mean level of insulin (176.95 pmol/L) hs-CRP levels (28.02 nmol/L) detected." (PMID 35846489, 2022). "Several cross-sectional studies have shown that CRP levels are associated with obesity, increased fasting blood sugar levels, and impaired insulin sensitivity, all components of insulin resistance." (PMID 35883605, 2022). "To date, the mechanisms underlying the potential protective role of CRP and leptin-to-adiponectin ratio (a suggested surrogate marker of insulin resistance) in breast carcinogenesis among premenopausal women are unclear and should be explored in experimental studies." (PMID 35430795, 2022). "Previous studies have shown that increased CRP levels are associated with insulin resistance, maternal dysglycemia and GDM, which may cause macrosomia." (PMID 35513792, 2022). "Elevated CRP levels are associated with insulin resistance, which could be a possible explanation for the worsening of dyslipidemia seen in RA." (PMID 36654631, 2022). "Moreover, insulin resistance is known to be associated with increased levels of proinflammatory cytokines such as C-reactive protein, tumour necrosis factor- (TNF-) α, interleukin- (IL) 1, and IL-6." (PMID 33597002, 2021). "Moreover, the serum level of high-sensitivity CRP are associated with β-cell dysfunction and insulin resistance." (PMID 34803906, 2021). "Evidence for the association of an inflammation-related insulin resistance phenotype with schizophrenia attenuated fully in MVMR analysis after adjusting for CRP, suggesting that these associations may be underpinned by inflammation." (PMID 33711016, 2021). "Second, the included populations mostly had baseline mean CRP levels between 1 and 10 mg/L (eTable 2 in the Supplement), suggesting a low grade of chronic inflammation normally associated with atherosclerosis and insulin resistance." (PMID 33710289, 2021). "Finally, adiponectin reductions are associated with increased CRP and other pro-inflammatory cytokines, insulin resistance, elevated plasma triglycerides and lipoproteins, and endothelial dysfunction in the general population." (PMID 34873143, 2021). "While BMI was associated with markers of insulin resistance and the association with the clustered cardiometabolic risk score was stronger than with rHGS, rHGS was more strongly associated with arterial stiffness and, more importantly, with hs-CRP." (PMID 33925420, 2021). "CRP and IL-6 are also implicated in pathogenesis of insulin resistance and may exaggerate the effects of insulin resistance on psychosis risk in young adults." (PMID 33711016, 2021). "Also, in another cross-sectional study representative of the Spanish population ≥ 18 years, higher adherence to the SEAD was associated with lower levels of C-reactive protein, triglycerides, insulin, insulin resistance, and systolic blood pressure." (PMID 33557823, 2021).